SEMA4A (semaphorin 4A)
Diseases named in the same sentence as SEMA4A in open-access papers (continued):
Sharing a sentence is not in itself a finding about the gene and the disease.
SEMA4A also shares sentences with these, for which no sentence is quoted: adenocarcinoma (2 papers); allergic asthma (2); degenerative diseases (2); infectious disease (2); systemic sclerosis (2); autoimmune disease (1); autoimmune thyroid disease (1); autoimmune uveitis (1); bronchiolitis (1); deafness (1); dominant cone-rod dystrophy (1); glaucoma (1); glioma (1); graft versus host disease (1); head and neck squamous cell carcinoma (1); juvenile idiopathic arthritis (1); keratoconus (1); Myasthenia (1); myasthenia gravis (1); non-small cell lung carcinoma (1); osteoarthritis (1); ovarian carcinoma (1); squamous cell carcinoma (1); Stroke (1); type 1 diabetes mellitus (1); ulcerative colitis (1).